INS (insulin)
Diseases named in the same sentence as INS in open-access papers (continued):
Sharing a sentence is not in itself a finding about the gene and the disease.
type 1 diabetes (continued). "Type 1 diabetes (T1D) is an autoimmune disease caused by the selective destruction of the pancreatic β-cells, lowering insulin production." (PMID 29249872, 2017). "Type 1 diabetes (T1D) is an autoimmune disease caused by the selective destruction of the pancreatic β-cells, causing inability to produce insulin." (PMID 29249872, 2017). "Type 1 diabetes mellitus (T1DM) is characterized by the immune-mediated depletion of β-cells, which results in deficient insulin secretion." (PMID 27478438, 2016). "Genetic association studies in type 1 diabetes have identified risk variants in the key genes responsible for autoimmune responses against insulin-derived peptides (HLA class II and class I genes, and the insulin gene), as well as in genes with prominent roles in CD4+ T cell function." (PMID 25652388, 2015). "Type 1 diabetes (T1D) is a chronic autoimmune disease that is characterized by the specific destruction of insulin‐producing pancreatic β cells, resulting in the loss of glycemic control." (PMID 26734463, 2015). "Type 1 diabetes (T1D) is an autoimmune disease characterized by the gradual loss of insulin-producing beta cells." (PMID 26080071, 2015). "Type 1 diabetes (T1D) is a disorder of glucose metabolism that results from insulin deficiency secondary to autoimmune destruction of insulin – secreting β cells." (PMID 24636465, 2014). "Thus, exploring the mechanisms responsible for glucose-regulated glucagon dysfunction in an insulin-deficient α-cell model may shed a light on the pathogenesis of glycemic instability in insulin-deficient type 1 diabetes." (PMID 25393115, 2014). "Type 1 diabetes mellitus (T1D) is an autoimmune disease which is associated with selective destruction of insulin producing β-cells." (PMID 25635252, 2014). "Finally, though not assessed in this study, it is becoming increasingly appreciated that subjects with type 1 diabetes may also be insulin resistant, a state which is associated with elevated cholesterol synthesis." (PMID 24376543, 2013). "Type 1 diabetes (T1DM) is a chronic inflammatory autoimmune disease characterized by destruction of insulin producing beta cells and by subsequent insulin deficiency." (PMID 23777480, 2013). "Type 1 diabetes (T1D) is an autoimmune disease wherein insulin deficiency results from the destruction of insulin-secreting β cells in the pancreas by infiltrating T cells and other cells of the immune system." (PMID 22123298, 2011). "Also in children with insulin-treated type 1 diabetes, the plasma ghrelin levels were found to be lower than those measured in controls with a negative association of their plasma ghrelin levels with daily insulin dosage." (PMID 21760816, 2011). "The genetic susceptibility of Type 1 diabetes is strongly associated with HLA-DQ and DR on chromosome 6, but genetic factors on other chromosomes such as the insulin gene on chromosome 11 and the cytotoxic T-lymphocyte antigen gene on chromosome 2 may modulate disease risk." (PMID 21504591, 2011). "Non-obese diabetic (NOD) mice spontaneously develop type 1 diabetes (T1D) due to the progressive loss of insulin-secreting β-cells by an autoimmune driven process." (PMID 19909804, 2010). "Finally, we apply a number of the methods to data for the INS gene associated with type 1 diabetes." (PMID 17508343, 2007). "In light of such findings, international guidelines recommend HCL systems as the preferred insulin delivery method in youth and adults with type 1 diabetes." (PMID 41024422, 2026). "Type 1 diabetes results from autoimmune destruction of the insulin-producing beta cells in the pancreas, requiring exogenous insulin for survival." (PMID 41037100, 2026). "To address this, we used a rodent STZ-induced type 1 diabetes model with basal insulin replacement and controlled recurrent hypoglycaemia, which allows better modelling of the human experience of hypoglycaemia and permits in vivo and ex vivo analysis." (PMID 41212210, 2026).
type 1 diabetes (continued). "This meta‐analysis (PROSPERO CRD42024606874) aimed to evaluate the efficacy and safety of once‐weekly basal insulin therapy in type 1 diabetes." (PMID 41048193, 2026). "A 12-wk randomized clinical trial found that adults with type 1 diabetes on a low-fat, vegan diet (n = 29) showed greater improvements in insulin sensitivity compared with a portion-controlled diet (n = 29)." (PMID 42211763, 2026). "For example, insulin, a hallmark autoantigen of type 1 diabetes (T1D), is detected in only a small fraction of mTEChi cells at relatively low levels, yet this expression is sufficient for negative selection as its depletion in mTECs leads to a breakdown of central tolerance and subsequent insulitis." (PMID 41461613, 2026). "A patient with long course of type 1 diabetes was treated with multiple injections of insulin, Android‐HCL therapy, and sequential multiple injections of insulin." (PMID 41568163, 2026). "The aim of this post hoc analysis was to evaluate bolus insulin patterns in newly diagnosed youth with type 1 diabetes using a hybrid closed-loop system, and to explore why the proportion of total daily insulin delivered as boluses decreases over time." (PMID 41571286, 2026). "Managing patients with type 1 diabetes (T1D) with end stage kidney disease (ESKD) on hemodialysis presents unique challenges due to altered insulin kinetics and rapid glucose fluxes." (PMID 42232681, 2026). "Type 1 diabetes treatment typically involves insulin administration via injections or insulin pumps, frequent blood glucose monitoring, and carbohydrate counting." (PMID 41540069, 2026). "Type 1 diabetes (T1DM) is characterized by the loss of β cells through autoimmunity and therefore the inability to produce insulin." (PMID 41131959, 2026). "While traditional interventions, such as exogenous insulin administration, can restore normoglycemia, cadaveric islet transplantation remains one of the most effective treatment options for type 1 diabetes (T1D)." (PMID 41048051, 2026). "Type 1 Diabetes (T1D) is a high-incidence chronic autoimmune disease, with patients requiring lifelong insulin therapy." (PMID 41737232, 2026). "Transplantation of allogeneic islets of Langerhans, which include the insulin-producing β cells of the endocrine pancreas, holds curative potential for type 1 diabetes (T1D)." (PMID 41480761, 2026). "Type 1 diabetes (T1D) results from autoimmune destruction of insulin-producing pancreatic islet β cells, resulting in life-long dependence on exogenous insulin." (PMID 41252212, 2026). "We carried out a 52 week, open label, randomised, controlled superiority trial including adult type 1 diabetes patients treated with insulin pumps." (PMID 41198916, 2026). "This reduction was smaller in individuals with type 1 diabetes and in those receiving insulin injections 3 or more times per day." (PMID 42040049, 2026). "We included randomized controlled trials (RCTs) comparing insulin icodec or efsitora against once‐daily basal insulins in people with type 1 diabetes." (PMID 41048193, 2026). "This study aimed to investigate the decline over time in the proportion of total daily insulin delivered as boluses in newly diagnosed youth with type 1 diabetes using a hybrid closed-loop system." (PMID 41571286, 2026). "Another area of our interest is the treatment of Type 1 Diabetes by conversion of intestinal epithelial cells into glucose-responsive insulin-producing, β-like cells." (PMID 41716816, 2026). "Type 1 diabetes (T1D) constitutes a chronic metabolic disorder attributed to the autoimmune destruction of insulin-producing pancreatic β cells, which most frequently occurs in childhood." (PMID 41897128, 2026). "In this case–control study from Ghana, we recruited 266 individuals with clinically diagnosed and insulin-treated long-term type 1 diabetes and 266 healthy control individuals." (PMID 41175199, 2026).
type 1 diabetes (continued). "After an overnight fast, participants ingested 60 g [6,6'-2H2]-glucose (D-Glc); subcutaneous insulin was administered to type 1 diabetes participants according to their carbohydrate-to-insulin ratio." (PMID 41686194, 2026). "Strengths of the present analysis include the long duration of hybrid closed-loop insulin delivery following diagnosis of type 1 diabetes in youth." (PMID 41571286, 2026). "Type 1 diabetes (T1D) is an autoimmune condition in which the insulin‐producing islets cells in the pancreas cease producing (or produce very little) endogenous insulin." (PMID 41572563, 2026). "Since its introduction in the 1920s, insulin therapy has been the cornerstone of treatment for type 1 diabetes." (PMID 41048193, 2026). "The aim of this work was to assess the effect of video consultations over 1 year compared with usual care for patients with type 1 diabetes treated with insulin pumps, with time in range (TiR) as the primary outcome measure." (PMID 41198916, 2026). "Our meta‐analysis is the first to evaluate the efficacy and safety of both insulin icodec and efsitora, focusing exclusively on people with type 1 diabetes and including all published RCTs." (PMID 41048193, 2026). "This meta‐analysis is the first to evaluate the efficacy and safety of once‐weekly basal insulin therapy exclusively in adults with type 1 diabetes and including all published RCTs." (PMID 41048193, 2026). "Type 1 diabetes is a chronic autoimmune condition resulting from immune-mediated destruction of pancreatic insulin-secreting beta cells and insulin insufficiency." (PMID 40598585, 2025). "Type 1 diabetes involves rigorous daily self‐care including monitoring blood glucose, insulin bolusing, adjusting insulin, as well as managing food and exercise." (PMID 41051982, 2025). "For instance, fluctuations in insulin secretion rates by pancreatic β cells in Type 1 Diabetes (T1D) or changes in thyroid hormone secretion by thyroid follicles in Hashimoto’s Thyroiditis (HT) can trigger symptom remission or relapse." (PMID 40416990, 2025). "Type 1 diabetes (T1D) is an autoimmune condition resulting from the immune-mediated destruction of the insulin-producing pancreatic beta-cells." (PMID 40726969, 2025). "Type 1 diabetes (T1D) is characterized by the autoimmune destruction of insulin-producing β cells within pancreatic islets, the specialized endocrine cell clusters of the pancreas." (PMID 40182604, 2025). "Exogenous insulin has been a longstanding treatment for type 1 diabetes and remains the standard of care." (PMID 40841367, 2025). "The purpose of this study was to develop a questionnaire to examine the future acceptance of Automatic insulin delivery systems (AIDs), their perceived usefulness, ease of use, and trust in the device in subjects with type 1 diabetes (T1D)." (PMID 39126517, 2025). "People with type 1 diabetes are insulin-dependent for life because their bodies cannot produce insulin." (PMID 40416402, 2025). "Type 1 diabetes (T1D) is a chronic condition characterized by the autoimmune destruction of the pancreatic beta cells that produce insulin." (PMID 39707844, 2025). "This enabled the maintenance of relatively stable blood insulin levels and effective glucose lowering, demonstrating the potential role of QE in the prevention and treatment of type 1 diabetes." (PMID 40807271, 2025). "Type 1 diabetes (T1D) is not only a disorder of insulin production from beta cell destruction, but also a progressive condition that brings about life-threatening complications such as diabetic nephropathy, impaired wound recovery, and cardiovascular disease." (PMID 40458682, 2025). "Type 1 diabetes (T1D) is a chronic autoimmune disease characterized by the selective destruction of insulin-producing β-cells within the islets of Langerhans, leading to insulin deficiency and chronic hyperglycemia." (PMID 41292817, 2025).
type 1 diabetes (continued). "Underlying reasons are most likely diverse, including psychological aspects specific to type 1 diabetes such as illness perceptions, coping strategies and insulin beliefs." (PMID 39755842, 2025). "People living with type 1 diabetes (T1D; approximately 300,000 in Canada) need to be administered subcutaneous insulin to maintain stable blood glucose (BG) levels and prevent long-term complications." (PMID 40153793, 2025). "The study group included patients with type 1 diabetes who had been receiving insulin therapy for 7.09 ± 3.41 years (range: 1–14.3 years)." (PMID 41377944, 2025). "Type 1 diabetes is an autoimmune disease with progressive destruction of insulin‐producing β cells in islets of Langerhans of the pancreas." (PMID 40716098, 2025). "Sodium–glucose cotransporter 2 (SGLT2) inhibitors have emerged as potential adjuncts to insulin therapy in type 1 diabetes due to their insulin-independent increase of renal glucose excretion." (PMID 40629004, 2025). "Type 1 diabetes (T1D) is a chronic autoimmune disease where pancreatic β-cells, responsible for secreting insulin in response to high glucose levels, are destroyed by the immune system through T cell-mediated immune response." (PMID 40710679, 2025). "In type 1 diabetes, an autoimmune condition characterized by the destruction of insulin-producing pancreatic beta cells, macrophages are part of the inflammatory response, which initiates insulitis and leads to pancreatic beta cell death." (PMID 41472730, 2025). "Patients with type 1 diabetes lack insulin; therefore, treatment focuses on insulin infusion therapeutics." (PMID 40921434, 2025). "Type 1 diabetes (T1D) is a chronic autoimmune condition that requires continuous self-management, including insulin therapy, blood glucose monitoring, dietary regulation, and physical activity." (PMID 41417781, 2025). "These elevated risks were particularly evident among individuals with type 1 diabetes, potentially reflecting the limitations of once‐weekly formulations in accommodating the dynamic insulin requirements characteristic of this population." (PMID 40509887, 2025). "Islet transplantation is a potential cure for type 1 diabetes (T1D), offering the possibility of insulin independence and improved glycemic control." (PMID 40666520, 2025). "In our study population, those using “insulin only” were likely to have type 1 diabetes, representing 2.7% of the total sample." (PMID 41350985, 2025). "Additional independent risk factors for progression to type 1 diabetes included ICA and GADA positivity, a diagnosis of gestational diabetes before age 30, and a requirement for insulin therapy during pregnancy." (PMID 40650275, 2025). "The Diabetes Control and Complications Trial (DCCT) demonstrated that intensive insulin regimens reduce the progression of albuminuria and delay microvascular complications in type 1 diabetes." (PMID 40534883, 2025). "Material and methods: prospective single-center study that collected data at 3 months and after isCGM implantation in pediatric patients with Type 1 diabetes, categorized according to their insulin regimen." (PMID 40863228, 2025). "In fact, some cases of fulminant type 1 diabetes have been reported to exhibit residual insulin secretion." (PMID 40406776, 2025). "Paired serum and DBS samples were collected from healthy controls (HC) and individuals with type 1 diabetes on insulin." (PMID 40386840, 2025). "One recent randomized trial demonstrated significant improvements in HbA1c and average glucose levels for people with type 1 diabetes (PWT1D) with HbA1c levels greater than 8.0% (64 mmol/mL) compared to a group using multiple daily insulin injections plus CGM." (PMID 39470803, 2025). "Attaining glycemic targets for people with type 1 diabetes (T1D) requires lifelong adherence to glucose monitoring and insulin therapy along with real-time adjustments to insulin delivery to account for variations in diet and activity." (PMID 41246816, 2025).
type 1 diabetes (continued). "Type 1 diabetes (T1D) is a chronic autoimmune disease characterized by the destruction of insulin-producing pancreatic beta-cells, whereas neighboring alpha, delta, and epsilon cells are mainly spared." (PMID 40028329, 2025). "In recent years, the availability of automated insulin delivery (AID) systems has improved the ability of people with type 1 diabetes to achieve the recommended glucose target ranges." (PMID 39653802, 2025). "The applicability of this model has been demonstrated by integrating it with a dynamic coarse-gained mathematical model of glucose-insulin regulation to study disrupted metabolic processes in Type I Diabetes (T1D) at a whole-body scale." (PMID 40470351, 2025). "Type 1 diabetes is a result of autoimmune destruction of insulin‐producing β‐cells in the pancreas, with genetic and multiple environmental factors acting as precipitators of the disease." (PMID 41157817, 2025). "A detailed cost-effectiveness analysis model for sotagliflozin compared with insulin monotherapy for patients with type 1 diabetes and chronic kidney disease demonstrated favorable economic outcomes." (PMID 41551500, 2025). "As an adjunct to insulin therapy, SGLT2i therapy can effectively reduce blood glucose levels, decrease body weight, and reduce insulin dosage requirements in patients with type 1 diabetes (T1D)." (PMID 40630104, 2025). "Insulin was isolated from the pancreas in 1921 and subsequently became a life-saving treatment for type 1 diabetes." (PMID 40565766, 2025). "This study evaluates the effectiveness of four commercially available automated insulin delivery (AID) systems in routine clinical practice for type 1 diabetes management and compares their first-year outcomes." (PMID 40666106, 2025). "If positive, close monitoring of blood glucose levels, HbA1c, and endogenous insulin secretion is essential for predicting and potentially delaying the onset of type 1 diabetes." (PMID 40650275, 2025). "The aim of this study was to explore the terminology used to describe insulin‐related disordered eating behaviors in people with type 1 diabetes and suggest consolidated terms to be used consistently going forward." (PMID 40958557, 2025). "Type 1 diabetes (T1D) is an endocrine disorder that occurs when pancreatic β cells cease generating insulin, usually as a result of autoimmune damage." (PMID 40519544, 2025). "Since there is currently no cure for type 1 diabetes, daily or continuous subcutaneous insulin injections are used to regulate blood sugar levels." (PMID 40299229, 2025). "Managing blood glucose after meals is a major challenge for subjects with type 1 diabetes, as both high and low glucose levels can occur depending on meal content, pre-meal insulin dosage, and individual variability." (PMID 40956852, 2025). "Effective management of DKA in young adults with type 1 diabetes necessitates a comprehensive approach that addresses insulin therapy, fluid resuscitation, electrolyte correction, vigilant monitoring, and preventive strategies to avert recurrence." (PMID 41149081, 2025). "Several mechanistically oriented immunomodulation trials attempting to preserve endogenous insulin production after diagnosis of type 1 diabetes have failed, while a few have showed promising initial results." (PMID 40768045, 2025). "Even though fulminant type 1 diabetes was indicated from the clinical course, insulin secretory ability improved." (PMID 40406776, 2025). "The autoimmune process that results in type 1 diabetes is characterised by the immune system attacking the pancreatic cells that produce insulin." (PMID 41361288, 2025). "In patients with type 1 diabetes, the insulin dose can be reduced and given only after food consumption, with the continuation of long-acting insulin." (PMID 40863223, 2025). "In type-1 diabetes (T-1D), insulin or glutamic acid decarboxylase 65 (GAD65) peptides are given in tolerogenic forms to promote immune tolerance." (PMID 40710338, 2025).